LILRA4 (leukocyte immunoglobulin like receptor A4)
Description:
Functions coreceptor to limit the innate immune responses to viral infections; signaling occurs via FCER1G. Down-regulates the production of IFNA1, IFNA2, IFNA4, IFNB1 and TNF by plasmacytoid dendritic cells that have been exposed to influenza virus or cytidine-phosphate-guanosine (CpG) dinucleotides, indicating it functions as a negative regulator of TLR7 and TLR9 signaling cascades. Down-regulates interferon production in response to interaction with BST2 on HIV-1 infected cells. Activates a signaling cascade in complex with FCER1G that results in phosphorylation of Src family and Syk kinases and thereby triggers mobilization of intracellular Ca(2+). Does not interfere with the differentiation of plasmacytoid dendritic cells into antigen-presenting cells.
Synonyms: CD85g; ILT7
Tractability: Antibody: a drug acting on it is in phase 2 or 3 trials; UniProt places it where antibodies can reach, with high confidence; its Gene Ontology location is reachable by antibodies, with high confidence; UniProt predicts a signal peptide or a membrane-spanning region. PROTAC: its protein half-life has been measured.
Gene: Protein-coding gene on chromosome 19 (54,333,185 to 54,339,162, reverse strand). Ensembl gene ENSG00000239961.
Subcellular location: Cell membrane
Pathways (Reactome):
Immune System: Immunoregulatory interactions between a Lymphoid and a non-Lymphoid cell
Gene Ontology:
Molecular function: coreceptor activity; protein binding; signaling receptor binding; inhibitory MHC class I receptor activity
Biological process: Fc-epsilon receptor signaling pathway; negative regulation of interferon-alpha production; negative regulation of toll-like receptor 7 signaling pathway; negative regulation of toll-like receptor 9 signaling pathway; negative regulation of tumor necrosis factor production; cytokine-mediated signaling pathway; immune response-inhibiting cell surface receptor signaling pathway; cell surface receptor signaling pathway
Cellular component: Fc-epsilon receptor I complex; plasma membrane
Genetic constraint (gnomAD): Loss-of-function variants: 53 observed, 52.06 expected, observed/expected ratio (o/e) 1.02, 90% interval 0.81 to 1.28. The upper end of that interval is the gene's LOEUF score, 1.28, which puts it in group 5 of 6, group 1 being the genes least tolerant of losing a copy. Missense variants: 624 observed, 642.16 expected, observed/expected ratio (o/e) 0.97, 90% interval 0.91 to 1.04. Synonymous variants: 272 observed, 269.76 expected, observed/expected ratio (o/e) 1.01, 90% interval 0.91 to 1.12.
Homologues: Orthologues: chimpanzee LILRA4 (96% identical), mouse Pira12 (49% identical), mouse Pira2 (49% identical), mouse Pira1 (48% identical), mouse Pira13 (48% identical), mouse Lilra6 (48% identical), rat Pirb (48% identical), rat LOC134485274 (47% identical), mouse Pirb (47% identical), rat Lilrb3 (43% identical), rat Lilrb2 (32% identical), rat Lilrc2 (28% identical), and 2 more. Paralogues in human: LILRB3 (66% identical), LILRA6 (66% identical), LILRA1 (60% identical), LILRA2 (60% identical), LILRB2 (59% identical), LILRB1 (58% identical), LILRB5 (58% identical), LILRA5 (35% identical), LILRB4 (31% identical), KIR3DL1 (26% identical), KIR3DL3 (25% identical), KIR3DL2 (25% identical), and 13 more.
Diseases named in the same sentence as LILRA4 in open-access papers:
LILRA4 is named in the same sentence as 17 diseases in open-access papers, as found by Europe PMC text mining. Sharing a sentence is not in itself a finding about the gene and the disease. The quoted sentences say what the papers report.
viral infection (7 papers, 2016 to 2024). "Studies of BST2-deficient mice imply a complex role in the regulation of viral infection; it also functions as an endogenous ligand for LILRA4, also known as ILT7, and inhibits cytokine production, although its precise biological roles remains contentious." (PMID 27359105, 2016). "LILRA4 is a coreceptor that controls innate immune responses generated through FCER1G in viral infection and acts as a negative regulator of TLR7 and TLR9 signaling cascades." (PMID 37435086, 2023). "Apart from its role in inhibiting viral release, BST2 also functions as an innate immune sensor during viral infections, activating NF-κB through interaction with ILT7/LILRA4 to induce inflammatory responses." (PMID 39840076, 2024).
bipolar disorder (2 papers, 2011 to 2022). A disorder of the brain that causes unusual shifts in mood, energy, activity levels and the ability to carry out day-to-day tasks. "A transcriptomic analysis of the dorsal striatum comparing individuals with bipolar disorder and controls found significant changes in the expression of 14 genes, including a few immune response genes, such as NLRC5, S100A12, LILRA4, and FCGB27." (PMID 36371440, 2022). "These genes included SBNO2, CEACAM5, AKAP1, UBC, ACTB, UBB, and FOS for schizophrenia; SEC24C, PGLYRP1, ARHGAP4, RPL22, SLC6A11, and SYK for bipolar disorder; and SRRT, PARK2, LILRA4, STK17A, IGFBP2, and NF1 for major depression." (PMID 22373040, 2011).
Miscarriage (2 papers, 2019 to 2023). A pregnancy that ends at a stage in which the fetus is incapable of surviving on its own, defined as the spontaneous loss of a fetus before the 22th week of pregnancy. "This was supported by the findings in a study on blood transcriptome in Holstein cows where LILRA4 was downregulated in the miscarriage cow group compared to the pregnant group." (PMID 37234872, 2023).
oral cancer (1 paper, 2025). "The genes PPT1 (palmitoyl-protein thioesterase 1), LILRA4 (leukocyte immunoglobulin-like receptor A4), and HCK (hemopoietic cell kinase) were correlated with a lower risk of oral cancer, while TNFRSF13C (tumor necrosis factor receptor superfamily member 13c) was linked to a higher risk." (PMID 40521000, 2025).
tumor (21 papers, 2016 to 2025). "More recently BST2 has been identified as a ligand for LILRA4, which is also expressed on several human cancers and downregulates IFN-α production, implying a mechanism through which tumours interact with LILRA4 to suppress immunity." (PMID 38022598, 2023). "Analysis of the tumour biopsies revealed that LILRA2, LILRA4, and LILRB4 were associated with the prognosis of PDAC patients." (PMID 36748687, 2023). "To validate the transcriptional data, we performed immunofluorescence microscopy on multiple advanced-stage MF samples staining for FPR2 and FCN1 to identify MF-specific tumor-associated macrophages (TAMs) and CLEC4C and LILRA4 to identify pDCs." (PMID 37669110, 2023). "pDCs are the only cell type known to express LILRA4 and are important in innate responses to viruses and tumours, producing significant quantities of IFNs following TLR7 and TLR9 ligation." (PMID 38022598, 2023). "LILRA4 and TLR9 were selected based on their well-delineated expression in multiplex fluorescence staining, using non-tumor tonsil tissue as a control." (PMID 37435086, 2023). "Our analysis also identified a subset of tumor-infiltrating pDCs in most of the MF samples that expressed TGFB1, ICOSLG, and LILRA4." (PMID 37669110, 2023). "LILRA2, LILRA4, and LILRB4 showed low expressions in tumour tissues, in which LILRB4 was significantly lowly expressed (p < 0.001)." (PMID 36748687, 2023). "DCs were further subdivided into cDC1 (cross-presenting dendritic cells; cluster 5 in Paratumor and cluster 11 in Tumor; CLEC9A+ and XCR1+), cDC2 (cluster 1 in Paratumor and cluster 1 in Tumor; CD1C+) and plasmacytoid DC (pDC; cluster 4 in Paratumor and cluster 13 in Tumor; LILRA4+ and IL3RA+)." (PMID 33429363, 2021).
cancer (12 papers, 2015 to 2024). A tumor composed of atypical neoplastic, often pleomorphic cells that invade other tissues. "A previous study reported that LILRA4 was also expressed in cancer cells, which was associated with impairment of plasmacytoid dendritic cells (pDCs) in the microenvironment of cancers." (PMID 36748687, 2023). "These genes were previously associated with pDC dysfunction in other human cancers that promoted an immunosuppressive TME by acting as negative regulators of type I IFN production via TGF-β and ILT7 (LILRA4) signaling." (PMID 37669110, 2023). "However, the functions of TRAV34, GTSF1L, LILRA4, and GNG8 in carcinoma remain unclear." (PMID 34844217, 2021). "In smokers, CLEC4C, LILRA4, and TLR9 levels were consistently higher than those in non-smokers; however, statistical significance was not reached, probably because of the immense proportion of epithelial components, including cancer cells (data not shown)." (PMID 37435086, 2023).
LILRA4 also shares sentences with these, for which no sentence is quoted: melanoma (3 papers); breast carcinoma (2); abortion (1); autoimmune disease (1); cutaneous lupus erythematosus (1); infection (1); lupus (1); major depression (1); rheumatoid arthritis (1); schizophrenia (1); seminoma (1).